MIR548H2 (microRNA 548h-2)
Synonyms: hsa-mir-548h-2; MIR548H-2; MIRN548H2
Gene: MicroRNA gene on chromosome 16 (11,306,440 to 11,306,527, reverse strand). Ensembl gene ENSG00000221801.
Gene Ontology:
Biological process: miRNA-mediated post-transcriptional gene silencing
Cellular component: RISC complex